ZNF200 (zinc finger protein 200)
Description:
Localizes protein arginine N-methyltransferase PRMT3 to the nucleus.
Tractability: PROTAC: ubiquitination databases record sites on it.
Gene: Protein-coding gene on chromosome 16 (3,222,324 to 3,236,221, reverse strand). Ensembl gene ENSG00000010539.
Subcellular location: Nucleus
Subcellular location (Human Protein Atlas): Mitochondria
Pathways (Reactome):
Gene expression (Transcription): Generic Transcription Pathway
Gene Ontology:
Molecular function: protein binding
Biological process: protein localization to nucleus
Cellular component: nucleus
Genetic constraint (gnomAD): Loss-of-function variants: 35 observed, 36.29 expected, observed/expected ratio (o/e) 0.96, 90% interval 0.74 to 1.28. The upper end of that interval is the gene's LOEUF score, 1.28, which puts it in group 5 of 6, group 1 being the genes least tolerant of losing a copy. Missense variants: 592 observed, 496.66 expected, observed/expected ratio (o/e) 1.19, 90% interval 1.11 to 1.28. Synonymous variants: 209 observed, 178.53 expected, observed/expected ratio (o/e) 1.17, 90% interval 1.04 to 1.31.
Homologues: Orthologues: chimpanzee ZNF200 (99% identical), macaque ZNF200 (97% identical), pig ZNF200 (84% identical), rabbit ZNF200 (84% identical), dog ZNF200 (82% identical), guinea pig ZNF200 (79% identical), Caenorhabditis elegans F57C9.4 (15% identical), zebrafish si:ch211-89o9.6 (15% identical), mouse Zfp65 (15% identical), Caenorhabditis elegans K09F6.6 (13% identical), Drosophila melanogaster CG9609 (12% identical), Caenorhabditis elegans F49C5.3 (9% identical), and 5 more. Paralogues in human: ZNF532 (27% identical), KRABD1 (3% identical).
Diseases named in the same sentence as ZNF200 in open-access papers:
ZNF200 is named in the same sentence as 5 diseases in open-access papers, as found by Europe PMC text mining. Sharing a sentence is not in itself a finding about the gene and the disease. The quoted sentences say what the papers report.
ovarian carcinoma (2 papers, 2010 to 2019). A malignant neoplasm originating from the surface ovarian epithelium. "The zinc finger protein 200 (ZNF200) is a little known gene and in cancer, only variants associated to ovarian cancer have been previously reported." (PMID 30940089, 2019).
cancer (3 papers, 2019 to 2023). A tumor composed of atypical neoplastic, often pleomorphic cells that invade other tissues. "The literature shows that some KZNFs are up-regulated in cancer, including ZNF695, ZNF320, ZNF200, ZNF354A, ZNF707, ZNF138 and so on." (PMID 37370088, 2023).
infection (1 paper, 2021). The state of being infected such as from the introduction of a foreign agent such as serum, vaccine, antigenic substance or organism. "We also identified one gene that demonstrates an effect in viral transcription and infection, namely ZNF200 (Zinc Finger Protein 200)." (PMID 33717105, 2021).
tumor (1 paper, 2019). "Within these 148 comparisons, significantly higher expression in normal tissues compared to tumor tissues was observed only in six cases (ZNF138 in KIRC and THCA, ZNF200 in THCA, ZNF273 in PRAD, ZNF485 in THCA, and ZNF789 in KICH)." (PMID 30444046, 2019).
ZNF200 also shares sentences with these, for which no sentence is quoted: colorectal cancer (1 paper).